GDF15 (growth differentiation factor 15)
Diseases named in the same sentence as GDF15 in open-access papers (continued):
Sharing a sentence is not in itself a finding about the gene and the disease.
diabetes (continued). "GDF-15 is considered a stress-induced cytokine, and it may play a role in various pathophysiological processes, e.g., heart insufficiency, myocardial infarction, pulmonary hypertension, diabetes, metabolic syndrome, autoimmune diseases and cancer." (PMID 34572118, 2021). "Patients with a higher level of GDF-15 were older, had a higher level of total cholesterol (TC), had a history of myocardial infarction and percutaneous coronary intervention or coronary artery bypass graft; and had a higher rate of hypertension, hyperlipidemia, and diabetes." (PMID 32746821, 2020). "However, patient with HF usually have some comorbidities such as hypertension, AF, stroke, diabetes, and chronic renal dysfunction, which may influence the circulating GDF-15 level and need to be eliminated." (PMID 33115406, 2020). "Therefore, in the present study, we hypothesized that serum GDF15 levels were correlated with LEAD as measured by ultrasonography in Chinese patients with type 2 diabetes mellitus (T2DM)." (PMID 32222153, 2020). "Moreover, the small size of the study population meant that it was not possible to explore the association between GDF-15 and incidence of diabetes." (PMID 30350239, 2019). "Secondly, because of the cross-sectional design, we can not predict whether elevated GDF-15 levels lead to increased risk of incident diabetes." (PMID 27642607, 2016). "Second, although the revealed heterogeneity was low for most of the comparisons, GDF-15 levels might be influenced by many factors, including age, male gender, current smoking, symptomatic heart failure, reduced kidney function, and diabetes mellitus, among others." (PMID 27154403, 2016). "In the final model with all predictors, VIF’s were the following: age = 1.22, sex = 1.04, hypertension or CVD = 1.18, diabetes = 1.26, cancer = 1.01, IL-6 = 1.27, TNFR1 = 1.99, IL-1b = 1.04, TNF-a = 1.55, IL-10 = 1.11, GDF15 = 2.16." (PMID 41280118, 2025). "The diabetes-resistant phenotype following hepatic and intestinal complex I inhibition is attributed to FGF21- and GDF15-dependent fat hunger signaling, which remodels adipose tissue into a glucose-metabolizing organ." (PMID 38267672, 2024). "However, studies also suggest that GDF15 contributes to ER stress‐induced β‐cell apoptosis, indicating that GDF15 inhibition may represent a novel strategy to promote β‐cell survival and support diabetes treatment." (PMID 39700016, 2024). "Hypertension and diabetes mellitus were significantly more prevalent and CACS values and HbA1c, NT-proBNP, and GDF-15 levels were significantly higher (all p < 0.001) in the elderly group compared to the middle-aged group." (PMID 37548881, 2024). "Furthermore, the current study revealed that GDF-15 levels were positively correlated with age, diabetes status, and NT-proBNP levels in HER2-positive breast cancer patients, which might explain the predictive value of GDF-15 for cardiotoxicity risk to some extent." (PMID 38828460, 2024). "Differences in GDF-15, ADMA, arginine/ADMA ratio, and IgG anti-MDA-LDL persisted even after adjusting for diabetes, smoking, and cholesterol." (PMID 39660078, 2024). "COVID-19 patients presenting with comorbidities including diabetes, cancer, chronic obstructive pulmonary disease (COPD) and cardiovascular disease had higher GDF-15 levels." (PMID 38686386, 2024). "Risk factors like advanced age, malegender, smoking, hypertension, diabetes mellitus, renal dysfunction,poly-vascular disease, hypertriglyceridemia, leucocytosis, and lowerconcentrations of hemoglobin and HDL-C were related to GDF-15 plasmaconcentrations." (PMID 39077481, 2023). "Growth differentiation factor 15 (GDF15) is a stress-inducible factor involved in the inflammatory progression of many complications, including type 2 diabetes mellitus (T2DM)." (PMID 36658625, 2023).
diabetes (continued). "Growth Differentiation Factor-15 (GDF-15) is a member of the TGF-β superfamily; increased levels have been reported in cases of heart failure, atherosclerosis, endothelial dysfunction and diabetes, and it is a prognostic biomarker in IPAH." (PMID 36835590, 2023). "In the stratification analysis by diabetic status, the association between genetically predicted GDF-15 and gallstones was consistently observed in nondiabetic participants (OR = 1.11, 95% CI: 1.01, 1.21; p = 0.003), indicating the observed association was not driven by diabetes." (PMID 35769993, 2022). "GDF15, a member of the tumor growth factor (TGF)-β superfamily, is involved in various pathological illnesses, including coronary artery disease, diabetes, and several cancer types." (PMID 35806043, 2022). "Consistent with previous reports, findings in this research showed that subjects with diabetes and CAD had higher levels of WBC, NEU, NLR, hs-CRP and GDF-15 than those with T2DM alone, indicating a more severe inflammatory state." (PMID 35842724, 2022). "However, the changes of glycemic control parameters were similar in the two subgroups (divided according to the median of ΔGDF15), which further proved that the elevation of serum GDF15 levels was not directly associated with glucose metabolism improvement in patients with type 2 diabetes mellitus." (PMID 36273168, 2022). "However, another study shows that baseline GDF15 levels are significantly higher in individuals who subsequently develop type 2 diabetes than in those who remain diabetes-free, but that these levels are not independently associated with the incidence of type 2 diabetes." (PMID 33003626, 2020). "Inverse relations between GDF-15 levels and testosterone were noted for almost all strata, stratified by categories of CAD risk factors, such as hs-CRP, leukocytes, neutrophils, neutrophil to lymphocyte ratio, glucose, HDL-c, and LDL-c and whether had hypertension, diabetes, and underwent PCI." (PMID 30819257, 2019). "GDF-15 is an anti-inflammatory cytokine, and other anti-inflammatory markers (such as TGF-β1) are also known to be elevated before the onset of diabetes." (PMID 30350239, 2019). "Patients with GDF-15 concentrations above the median were older, had longer diabetes duration, lower eGFR and LDL cholesterol and were more frequently treated with oral antidiabetic drugs than patients with GDF-15 concentrations below the median." (PMID 29698460, 2018). "Higher level of GDF-15 is associated with increased cardiovascular and noncardiovascular mortality; it plays pivotal role in development and progression of cardiovascular diseases such as heart failure, coronary artery diseases, atrial fibrillation, diabetes, cancer, and cognitive impairment." (PMID 26273671, 2015). "Interestingly, saturated fatty acids (FAs) such as palmitate, the primary saturated FA in most diets, activate the ER stress-UPR pathway, increasing the expression levels of GDF15 via CHOP and promoting insulin resistance and type 2 diabetes mellitus (T2DM)." (PMID 39825925, 2025). "In the post hoc study that included 190 heart failure patients predominantly without diabetes, empagliflozin increased plasma levels of GDF15." (PMID 40837873, 2025). "Age, TSH, history of diabetes, hypertension, and smoking positively correlated with GDF15, while FT4 and total cholesterol showed a negative association with GDF15." (PMID 41303556, 2025). "To investigate this issue, we screened out the patients without hypertension, hyperlipidemia, or diabetes in this current study and then analyzed the correlation between GDF-15 and cardiotoxicity." (PMID 38828460, 2024). "The diabetes group was also stratified into four groups based on GLS (above or below the cohort median of -9.9%) and plasma biomarker (above or below median for NT-proBNP, hs-TnT, GDF-15, sST2, and Gal-3)." (PMID 38443793, 2024).
diabetes (continued). "One group characterized by the prevalence of diabetes and kidney disease had the highest plasma concentrations of creatinine, glucose, gamma-glutamyl transferase (GGT), and growth differentiation factor-15 (GDF-15)." (PMID 38255869, 2024). "The diabetes group had higher NT-pro-BNP, hs-TnT, GDF-15, sST2, and Gal-3." (PMID 38443793, 2024). "DNAm-predicted GDF15 remained a significant predictor of mortality across individuals with or without hypertension, diabetes, cardiovascular disease, chronic kidney disease, or cancer." (PMID 39625596, 2024). "Treating human islets with GDF15 prevented the apoptosis induced by IL-1β and IFNγ, and administration of GDF15 to non-obese diabetic (NOD) mice prevented the development of diabetes." (PMID 37761001, 2023). "In this post-hoc study of 187 HFrEF patients predominantly without diabetes, we found that treatment with empagliflozin led to an 9% increase in plasma GDF-15 compared to placebo after 12 weeks of treatment." (PMID 35219331, 2022). "A population prospective cohort study carried out in Sweden reported that increased GDF-15 levels were related with incident CKD and a decline in eGFR in the general population, independent of potential risks of death like cardiovascular disease and diabetes." (PMID 35204349, 2022). "Patients with diabetes and treated with metformin demonstrated no increase in plasma GDF-15 with empagliflozin, p for interaction = 0·01." (PMID 35219331, 2022). "GDF-15 is upregulated by ageing, renal dysfunction, diabetes, CV diseases, inflammation, and is not specific for the heart." (PMID 34358298, 2022). "Since GDF15, endostatin, and CXCL16 are suggested to be biomarkers of CKD, our data suggest that VEGF-D may have a role as a biomarker in diabetic CKD." (PMID 35363168, 2022). "Of course, varying elevations in serum FGF21 and GDF15 levels also exist in non-neuromuscular diseases, including diabetes, liver diseases, kidney diseases, tumours, heart diseases, and respiratory diseases." (PMID 35498801, 2022). "In the small group of patients with diabetes and who were treated with metformin there was no increase in plasma GDF-15 with empagliflozin, p for interaction = 0.01." (PMID 35219331, 2022). "The present study first found that the increase of serum GDF15 levels after metformin intervention was not related to the improvement of glycemic control parameters (ΔFPG, Δ2-h PG or ΔHbA1c) in patients with type 2 diabetes mellitus." (PMID 36273168, 2022). "Whole-body fat, trunk fat, and appendicular fat mass did not correlate with GDF15 levels when controlling by metabolic syndrome and diabetes." (PMID 35160008, 2022). "Using data from large biobanks, we found that neither MR nor GDF15 PTV analyses supported a causal role for GDF15 plasma levels in influencing BMI, glucose, diabetes, or eBMD in humans." (PMID 35916366, 2022). "Second, our interaction analysis revealed tendency toward no increase in plasma GDF-15 in patients with diabetes, and significant for those few patients who were on metformin treatment." (PMID 35219331, 2022). "Leptin, adiponectin, GDF-15 and FGF-21 changes were related to weight loss not remission of diabetes." (PMID 33925808, 2021). "In our study, higher GDF-15 levels were seen in older patients with longer time in RRT, but no other clinical characteristics (such as sex or diabetes) or laboratory findings were associated with its value." (PMID 33419237, 2020). "In contrast to other established CVD biomarkers, GDF-15 is also strongly related to numerous non-cardiovascular conditions such as kidney diseases, diabetes mellitus, neoplasia and cancer-induced anorexia, or rheumatoid arthritis." (PMID 32993054, 2020). "Hence serum GDF-15 and TNC can be considered as one of the parameters for predicting and diagnosis of an acute coronary event in patients with type 2 diabetes mellitus." (PMID 33312062, 2020).
diabetes (continued). "Metformin and other biguanides such as phenformin were shown to induce GDF-15 expression in murine and human hepatocytes, while the direct effect of other anti-diabetes drugs has not been studied yet." (PMID 33312159, 2020). "Growth Differentiation Factor-15 (GDF-15) is a cytokine acting as a marker of oxidative stress; it plays a role in multiple diseases including cardiovascular disease, various cancers, renal failure, diabetes mellitus and inflammatory diseases." (PMID 32466218, 2020). "Between 1991 and 1994, baseline fasting plasma GDF-15 levels were measured in 4360 individuals without diabetes (mean age 57.4 ± 5.96 years, 38.6% men) who were participants in the Malmö Diet and Cancer–Cardiovascular Cohort." (PMID 30350239, 2019). "Significant associations between GDF15 levels and CRP levels have previously been reported in patients with non-ST elevation acute coronary syndrome, diabetes, morbid obesity, and cancer." (PMID 28798540, 2017). "Plasma GDF-15 levels have been found to be positively correlated with abdominal obesity and insulin resistance in obese subjects without diabetes." (PMID 27642607, 2016). "Growth differentiation factor 15 (GDF15), a divergent member of the transforming growth factor-β (TGF-β) superfamily, is a stress-response cytokine related to a wide variety of metabolic diseases, including type 2 diabetes mellitus (T2D) and cardiovascular (CV) disease, among other conditions." (PMID 39596055, 2024). "The one patient who experienced cardiotoxicity had a GDF-15 level of 889 pg/mL; the number was higher than the median level 703.5 pg/mL of those without cardiotoxicity in the cohort without hypertension, hyperlipidemia, or diabetes." (PMID 38828460, 2024). "Interestingly, the addition of GDF-15 to the prognostic model resulted in NT-proBNP and diabetes becoming non-significant as predictors of first HHF and all-cause mortality." (PMID 37567614, 2024). "Consequently, GDF15 expression is upregulated in chronic inflammatory diseases, cardiovascular disease, non‐alcoholic fatty liver disease (NAFLD) and diabetes." (PMID 35510313, 2022). "Previously, GDF-15 has been examined as a biomarker to indicate CVD risk and all-cause mortality in three meta-analyses of patients with HF and/or acute coronary syndrome, irrespective of diabetes status." (PMID 35883490, 2022). "However, recent studies have suggested that treatment with NAG-1/GDF15 inhibits diabetes in 53% of non-obese diabetic mice." (PMID 34294853, 2021). "Moreover, diabetes is not an established risk factor for lobar ICH and SAH, which makes it likely that other effects of GDF-15 are important." (PMID 34177769, 2021). "We first evaluate GDF15 concentration within several subgroups, including diabetes mellitus (no vs. yes), previous history of cardiovascular disease (no vs. yes), different CKD stages (CKD stage 1 + 2 group vs. 3 vs. 4 + 5) and uPCRs (uPCR <30mg/g vs. 30–300mg/g vs. >300mg/g)." (PMID 33567936, 2021). "However, even after excluding all LD patients with diabetes mellitus from the calculation, GDF15 is still significantly elevated in the LD cohort (data not shown)." (PMID 33003626, 2020). "The purpose of our study was to investigate the relationship between plasma growth differentiation factor-15 (GDF-15) concentrations and diabetic retinopathy in patients with type 2 diabetes mellitus (DM)." (PMID 33239667, 2020). "In contrast, the treatment of diabetes does not interfere with GDF-15." (PMID 31630688, 2019). "Furthermore, in CAD patients with hypertension, and diabetes or not, testosterone correlated significantly with GDF-15." (PMID 30819257, 2019). "It has been suggested that upregulation of GDF-15 occurs in response to inflammation that precedes diabetes, but that this upregulation is not sufficient to compensate for the chronic low-grade inflammation, which leads to metabolic disorders such as β cell dysfunction and insulin resistance." (PMID 30350239, 2019).
diabetes (continued). "In addition, GDF-15 levels are higher in obese individuals with (than in those without) impaired glucose tolerance, and are also higher in people with diabetes than in those without it." (PMID 30350239, 2019). "Finally, the patients in the present study were mainly without diabetes, and the effects of empagliflozin on plasma GDF-15 may be different in populations of HFrEF patients with a higher prevalence of diabetes and/or in severe HFrEF patients." (PMID 35219331, 2022). "The ability of GDF-15 to produce metabolic benefits by improving insulin resistance may explain the improvement in insulin resistance that was induced by empagliflozin in patients with HFrEF without concomitant diabetes." (PMID 35219331, 2022). "Previous studies found that the levels of serum GDF15 were usually proportional to age and SBP, positively correlated with FPG, HbA1c, and Hcy in diabetes, while negative correlated with TC, and BMI in monozygotic twin pairs." (PMID 36658625, 2023). "In obese non-diabetic individuals, GDF-15 could predict future insulin resistance and impaired glucose control, and in patients free of clinically-overt cardiovascular disease, GDF-15 was positively associated with age, diabetes, hypertension, worse kidney function and NT-proBNP levels." (PMID 25171167, 2014). "Anti-inflammatory drugs such as the nonsteroidal anti-inflammatory drugs (NSAID) can induce GDF15 expression, and VLDC can significantly reduce low-grade inflammation of type 2 diabetes mellitus patients." (PMID 23799024, 2013). "Therefore, we conclude that the ability of circulating GDF15 at diagnosis to predict the highest tertile of BVAS remained significant, regardless of the presence of diabetes mellitus in patients with AAV." (PMID 40142684, 2025).